PLCB1 (phospholipase C beta 1)
Diseases named in the same sentence as PLCB1 in open-access papers (continued):
Sharing a sentence is not in itself a finding about the gene and the disease.
delirium (1 paper, 2020). A disorder characterized by confusion; inattentiveness; disorientation; illusions; hallucinations; agitation; and in some instances autonomic nervous system overactivity. "The misregulation of the four HAR-Brain genes, namely APP, PLCB1, NPY, and HTR2A, in the M1 module is more likely to underlie delirium susceptibility rather than specifically be the molecular pathways driving the development of delirium." (PMID 33086708, 2020). "We found that four of the HAR-Brain genes, namely APP, PLCB1, NPY, and HTR2A, in the M1 module were highly connected and appeared to exhibit hub properties, which might play vital roles in delirium development." (PMID 33086708, 2020).
developmental and epileptic encephalopathy (1 paper, 2025). An epilepsy associated with developmental impairment that may be due to either the underlying etiology or the superimposed epileptic activity, or both. "PCDH19, PLCB1, SCN8A, and HCN1 variations were found in Late Infantile Developmental and Epileptic Encephalopathy (LIDEE) patients." (PMID 41153369, 2025).
erythroleukemia (1 paper, 2024). Acute erythroid leukemia characterised by the presence of at least 50% erythroid precursors and at least 20% myeloblasts in the bone marrow. "For example, PLCB1 can significantly increase the expression levels of Cyclin D3 and the percentage of S phase cells in the K562 human erythroleukemia cell line." (PMID 38731807, 2024).
heart transplant (1 paper, 2021). "Furthermore, PLCB1 rs170549 has previously been associated with eGFR in adult heart transplant recipients, although the study did not describe which allele was associated with worse renal function, nor the magnitude of the association." (PMID 33868389, 2021).
herpes simplex infection (1 paper, 2019). "For the thymus, the NOD-like receptor signaling pathway (PLCB1/MAPK11), the MAPK signaling pathway (SRF/MAPK11), influenza A (RSAD2/MAPK11), and MAPK11 (salmonella, toll-like, herpes simplex infection) were observed." (PMID 30769908, 2019).
hidradenitis suppurativa (1 paper, 2024). A chronic suppurative and cicatricial disease of the apocrine glands occurring chiefly in the axillae in women and in the groin and anal regions in men. "Interestingly, PLCB1 was also identified in the blood methylome analysis of hidradenitis suppurativa (HS) patients." (PMID 38931955, 2024).
infantile epilepsy (1 paper, 2014). "PLCB1-EIEE is now reported in a number of different EIEE phenotypes and our report provides further evidence for phenotypic pleiotropy encountered in early infantile epilepsy syndromes." (PMID 24684524, 2014).
insomnia (1 paper, 2011). A sleep disorder characterized by difficulty in falling asleep and/or remaining asleep. "Hence, dysregulation of ROR1, PLCB1, or PLCB4 by PAX6 and CTCF may be one mechanism that links neural and pancreatic dysfunction not only in insomnia but also in the relevant psychiatric disorders that are accompanied with circadian rhythm disruption and metabolic syndrome." (PMID 21494683, 2011).
ischemia (1 paper, 2021). A hypoperfusion of the BLOOD through an organ or tissue caused by a PATHOLOGIC CONSTRICTION or obstruction of its BLOOD VESSELS, or an absence of BLOOD CIRCULATION. "In addition, mRNA and protein levels of PLCβ1 are increased in ischemia and in stroke-prone SHRs as young as 8–10 months there is increased sarcolemmal protein kinase C (PKC) activity, suggesting increased PLCβ1 activity." (PMID 35002765, 2021).
leukemia (1 paper, 2024). A malignant (clonal) hematologic disorder, involving hematopoietic stem cells and characterized by the presence of primitive or atypical myeloid or lymphoid cells in the bone marrow and the blood. "This study revealed the transcriptomic change of HSPCs in MDS patients along the pseudotime and indicated that PLCB1 plays a key role in the transformation of MDS into leukemia." (PMID 38632656, 2024). "We found the major amplifying population in HSPCs in MDS with excess blasts (EB) (MDS-EB)/secondary AML is CMP and the high expression of PLCB1 might play an important role in the transformation of MDS into leukemia." (PMID 38632656, 2024). "In addition, we found PLCB1 plays an important role in the transformation of MDS into leukemia." (PMID 38632656, 2024).
memory impairment (1 paper, 2021). "Together, these results indicate that PLCβ1 protein levels are related to successful memory recall and that increasing PLCβ1 protein levels could restore contextual fear memory impairment in AD mice." (PMID 34625112, 2021). "Taken together, our results suggest that enhancing eCB mobilization by increasing PLCβ1 protein levels could have therapeutic potential for restoring memory impairments in both early and chronic stages of AD." (PMID 34625112, 2021). "Considering that increasing the PLCβ1 protein levels can restore AβO-impaired tLTP, and that tLTP is the most probable synaptic mechanism underlying learning and memory, we hypothesized that increasing PLCβ1 protein levels could also restore behavioral memory impairment in AD." (PMID 34625112, 2021). "Next, to determine whether a decrease in PLCβ1 protein levels correlates with hippocampus-dependent memory impairment in a mouse model of AD, we performed a contextual fear memory task in the DMSO-injected WT, DMSO-injected 5XFAD, and m-3M3FBS-injected 5XFAD mice." (PMID 34625112, 2021). "Moreover, we found that hippocampal PLCβ1 protein levels in the 5XFAD mouse model of AD were also decreased and that direct hippocampal injection of m-3M3FBS in vivo in the 5XFAD mice fully restored the hippocampus-dependent contextual fear memory impairment in 5XFAD mice." (PMID 34625112, 2021).
neuropathic pain (1 paper, 2017). Chronic pain caused by damage to nerve fibers. "On the other hand, there were no changes in the expression of mRNA of Plcβ1 mRNA in DRGs or in the spinal cord of rats with CCI-induced neuropathic pain." (PMID 28373843, 2017).
neuropathy (1 paper, 2025). A disorder affecting the nervous system that manifests with pain, tingling, numbness, and/or muscle weakness. "The rs6086563 SNP identified in the phospholipase C-beta 1 gene may affect myo-inositol depletion, thereby increasing the risk of developing microvascular complications such as neuropathy." (PMID 40650017, 2025).
oligodendroglioma (1 paper, 2016). A well-differentiated (WHO grade II), diffusely infiltrating neuroglial tumor, typically located in the cerebral hemispheres. "We also analyzed oligodendroglioma cases separately and found that PLCβ1 expression is inversely related to pathological grades." (PMID 26614510, 2016).
ovarian dysfunction (1 paper, 2019). The inability of the ovaries to function. "Additionally, PLCB1 was previously identified as a positional candidate gene for primary ovarian failure and ovarian dysfunction in humans, suggesting that PLCB1 may have a crucial role in early pregnancy success." (PMID 31766405, 2019).
pancreatitis (1 paper, 2022). Inflammation of the pancreas. "The relationship between SNHG11 and PLCB1 genes and the progression of inflammation in vivo may be one of the important reasons pancreatitis causes systemic organ failure." (PMID 36611865, 2022). "It is confirmed that SNHG11 plays a role in pancreatitis through this pathway axis (lncRNA-SNHG11/miR-7-5p/PLCB1)." (PMID 36611865, 2022). "In our article, we demonstrated the role of the MIR17HG/miR-7-5p/PLCB1 axis in pancreatitis for the first time." (PMID 36611865, 2022). "This is the first report of the lncRNA-SNHG11/miR-7-5p/PLCB1 pathway axis and the first report of miR-7-5p and PLCB1 genes in pancreatitis." (PMID 36611865, 2022). "In conclusion, this article shows the role of the lncrna-SNHG11/mir-7-5p/PLCB1 axis in pancreatitis for the first time, and once again, confirms the important role of non-coding RNA in pancreatitis." (PMID 36611865, 2022). "We hope to investigate the specific pathways of the SNHG11/miR-7-5p/PLCB1 axis after confirming its role in pancreatitis progression." (PMID 36611865, 2022). "The results showed that PLCB1 was significantly downregulated in pancreatitis at the transcriptional and protein expression levels." (PMID 36611865, 2022). "In our study, we discovered the relationship between the new target molecules SNHG11 and PLCB1 genes and inflammatory cytokines in pancreatitis and confirmed the regulation of SNHG11 and PLCB1 genes on inflammatory cytokines in vitro in vivo experiments." (PMID 36611865, 2022). "Our results showed that the effect of miR-7-5p on promoting pancreatitis progression was restored by PLCB1 expression, and the effect of miR-7-5p on promoting inflammatory factors was also restored by PLCB1." (PMID 36611865, 2022). "For the first time, the role of PLCB1 in pancreatitis progression was confirmed, and it was discovered that PLCB1 could affect the release of inflammatory factors, which may be related to its important role in intracellular signal transduction." (PMID 36611865, 2022). "However, there are few reports on PLCB1 and inflammatory progression, especially the role of PLCB1 in pancreatitis." (PMID 36611865, 2022). "More importantly, as an important signaling pathway in the pancreatitis cascade reaction, our findings confirmed the correlation between the PLCB1 and the P38MAPK signaling pathways, opening up new avenues for future research into the PLCB1 and P38MAPK signaling pathways." (PMID 36611865, 2022). "Therefore, our results demonstrate the role of the SNHG11/miR-7-5p/PLCB1 axis in pancreatitis progression." (PMID 36611865, 2022). "Therefore, we then verified the role of PLCB1 in pancreatitis." (PMID 36611865, 2022). "Furthermore, we found that lncRNA-SNHG11 could attenuate the effect of miR-7-5p on the transcriptional inhibition of PLCB1 through adsorption to miR-7-5p and delay the progression of pancreatitis." (PMID 36611865, 2022). "At the same time, combined with our sequencing files and the microarray data of pancreatitis in GEO (GSE120138) for screening, the results suggest that PLCB1 may be a potential downstream target of miR-7-5p and be involved in the progression of pancreatitis." (PMID 36611865, 2022).
pregnancy disorder (1 paper, 2017). A disorder that is related to pregnancy. "Finally, we also identified five genes (PLCB1, LUM, ADCY7, IRF7, and EHHADH) that we predict to be important for pregnancy disorders and placenta development, although such links remains to be established." (PMID 29222466, 2017).
prostate carcinoma (1 paper, 2025). A carcinoma that arises from epithelial cells of the prostate gland. "PLCB1 is overexpressed in adipose tissues of prostate cancer patients." (PMID 41009685, 2025).
psychosis (1 paper, 2014). "A way of conceptualizing the affective dimension of psychosis proposes a biochemical nomenclature: PLCβ1-/-, PLCβ1-/+ and PLCβ1+/+, where + and – represent normal and deficient allelic or pathway expression to a balanced ERK and Akt activation." (PMID 25566074, 2014). "Although mutations in the PLCB1 gene could potentially be used as a marker differentiating a nosology of psychosis, the converse does not necessarily apply." (PMID 25566074, 2014).
renal dysfunction (1 paper, 2021). "Two SNVs, TGFB1 rs4803455 and PLCB1 rs170549, were associated with renal dysfunction 1-year post-transplant after accounting for an FDR of 20%." (PMID 33868389, 2021). "We also found that carriers of the intronic PLCB1 rs170549 variant A allele had higher odds of renal dysfunction when compared to individuals with the G/G genotype." (PMID 33868389, 2021). "In contrast, PLCB1 rs170549 variant A allele carriers had higher odds of renal dysfunction than G/G homozygotes (OR 2.66; 95% CI 1.21–5.84; p = 0.015)." (PMID 33868389, 2021). "Two SNVs [transforming growth factor beta 1 (TGFB1) rs4803455 C > A and phospholipase C beta 1 (PLCB1) rs170549 G > A] were significantly associated with renal dysfunction 1-year post-transplant in the univariate analyses after adjusting for an FDR of 20% (unadjusted p = 0.004 for both SNVs)." (PMID 33868389, 2021). "Renal dysfunction was present in 43% of participants with the TGFB1 rs4803455 C/C genotype vs. 22% of variant A carriers, and 20% of participants with the PLCB1 rs170549 G/G genotype vs. 39% of variant A carriers." (PMID 33868389, 2021). "In conclusion, we provide additional evidence that SNVs in the pro-fibrotic TGFB1 and cell signaling PLCB1 genes may play a role in the development of renal dysfunction in adult heart transplant recipients taking CNIs." (PMID 33868389, 2021). "Thus, additional studies are needed to elucidate the mechanism by which PLCB1 rs170549, or a functional SNV linked with this intronic variant, influences the development of renal dysfunction in heart transplant recipients receiving CNIs." (PMID 33868389, 2021). "Novel genetic markers, such as TGFB1 rs4803455 and PLCB1 rs170549, may serve as tools that clinicians can utilize to assess a patient’s risk of CNI-associated renal dysfunction following heart transplantation, thereby improving clinical care and advancing precision medicine in this population." (PMID 33868389, 2021). "Pharmacogenetic markers, such as TGFB1 rs4803455 and PLCB1 rs170549, could help identify patients at increased risk of CNI-associated renal dysfunction following HTx, potentially allowing clinicians to provide more precise and personalized care to this population." (PMID 33868389, 2021).
substance dependence (1 paper, 2017). The psychological or physiological need to take a substance in order to experience its effects or to avoid the effects of its absence. "A region of overlapping clusters of SNPs in the PLCB1 gene were identified in a previous study that assessed common genomic regions in two GWAS of illegal substance dependence and cocaine dependence." (PMID 28860459, 2017).
cancer (27 papers, 2012 to 2025). A tumor composed of atypical neoplastic, often pleomorphic cells that invade other tissues. "Since EVs/GHCer-mediated angiogenesis is linked to TRAX/PLCβ1/Ca2+ signaling pathway, development of novel anti-cancer drugs that could disrupt the GHCer/TRAX interaction may provide a new strategy for the treatment of GHCer-positive cancer." (PMID 36517806, 2022). "Nevertheless, the reduced abundance of genus Paeniclostridium and genus Enterococcus in cancer tissues also exhibited significant associations with the expression difference of PLCB1 (r = 0.995, p-value = 0.01, df = 2) and IGSF9, respectively (r = − 0.997, p-value = 0.003, df = 2)." (PMID 32321427, 2020). "To investigate the effects of reduced PLCβ1 on the main molecular mechanisms that regulate cancer development, we examined the physiological and pathological processes required for cell migration and invasion." (PMID 35303162, 2022). "Separate from other known cancer biomarkers, which are usually upregulated at different stages of a disease, PLCβ1 expression level is the highest in normal tissues." (PMID 26614510, 2016). "PLC β1 was described to be selectively increased during myoblast and adipocyte differentiation, and evidences suggested that deletion of PLCB1 favours cancer progression in the myeloid lineage." (PMID 27026853, 2016). "Overexpressed genes in the PP adipose tissue of cancer patients that are involved in cell cycle and proliferation include PLCB1, that modulates cyclin D3 and CDK4 in response to the IGF-1 mitogenic stimulus or TPPP3, that regulates G2-M and G1-S transitions." (PMID 23009291, 2012). "PLCB1, -2, and -3 were shown to alter various pathways in different cancers." (PMID 36927770, 2023). "It is well known the role of β-Catenin, a component of the cell–cell adhesion complex, in the regulation of proliferation and migration in different cell types and cancers, and interestingly, the active form of this protein is overexpressed in all our PLCβ1-silenced models." (PMID 35303162, 2022). "Based on these results, the expression of ITGA2, BMP4 and PLCB1 may contribute to cancer development." (PMID 28947976, 2017). "Besides, ROCK1 targeted by hsa-miR-4689 and PLCB1 targeted by hsa-miR-3911 were significantly involved in Proteoglycans in cancer, and PLCB1 was Rap1 signaling pathway and Glutamatergic synapse (FDR = 0.022324586)." (PMID 26879603, 2016). "The requirement for these small molecules thus restricts the enzymatic activity of PLCβ1, and the location of these small molecules in the tumor microenvironment may drive directional cancer cell migration." (PMID 26620550, 2016). "Interestingly, the expression of PLC genes which codify for PLC isoforms supposed to favour cancer progression was reduced, while the expression of PLCB1, which was thought to favour differentiation and/or apoptosis, was increased." (PMID 27026853, 2016). "Therefore, targeting PLCB1 and DESC1 could be potential strategies for inhibiting the resistance to MEK1/2 inhibition in certain cancers with NRAS or BRAF mutations." (PMID 34064422, 2021). "Thus, increase in PLC β1 protein and PLCB1 transcript levels might be actually considered to unfavour cancer progression and/or favour differentiation." (PMID 27026853, 2016). "Interestingly, we find that both PTPRN2 and PLCβ1 localize to the plasma membrane, and demonstrate prominent localization to one edge of the plasma membrane, presumably corresponding the leading edge of the cancer cell (Fig EV3A)." (PMID 26620550, 2016). "Given that PLCB1 is one of the key regulators in signal transduction or an important tumor suppressor genes, it is possible that one or more of these SNPs may change the expression of PLCβ1 or modify protein interactions that might manipulate the development of cancer." (PMID 25683757, 2015).